ANGPT2 (angiopoietin 2)
Diseases named in the same sentence as ANGPT2 in open-access papers (continued):
Sharing a sentence is not in itself a finding about the gene and the disease.
tumor (continued). "Many studies aim to block the binding of ANGPT1/ANGPT2 to TIE-2, thereby, inhibiting tumour growth." (PMID 31217905, 2019). "In addition, it has been demonstrated that tumour cells are able to produce angiopoietin-2, which recruits TIE-2 expressing monocytes (TEM) into the tumour site." (PMID 31554160, 2019). "Embryonic development, menstrual cycle, hypoxia, inflammation, and tumor will stimulate angiogenic signals, such as vascular endothelial growth factor (VEGF), angiopoietin-2 (ANG-2), and fibroblast growth factors (FGFs) to sprout new endothelial cells and pericytes or vascular smooth muscle cells." (PMID 30151069, 2018). "Whether this finding could be due to a race-related difference in the tumor’s responsiveness to bevacizumab is deserving of further study to fully evaluate if ANGPT1, ANGPT2, TEK, FGF2, MMP9 and VEGFA are promising targets for future research." (PMID 28045923, 2017). "Regarding the activation of tumor angiogenesis, the most prominent targets of HIF-1α are vascular endothelial growth factor (VEGF), calcitonin receptor-like receptor (CRLR), stem cell factor (SCF) and angiopoietin 2 (ANGPT2)." (PMID 27929432, 2016). "The ANGPT1/ ANGPT2 transcription ratio was found decreased in larger tumours and especially in tumours without lymphatic spread." (PMID 26044849, 2015). "Remarkable results identified by our data were the 2.7- and 2.9- fold gene expression level of VEGF and ANGPT2 in poorly differentiated tumours with lymph node metastasis versus those without." (PMID 26044849, 2015). "Furthermore, we demonstrated that ZIC1 can suppress the expression of other novel genes (TACSTD2, ANGPT2, LAMB2, LAMB3 and MALAT1 etc.)related to tumor angiogenesis and metastasis." (PMID 21347233, 2011). "Angiopoietin-1 (Ang-1) maintains pericyte/endothelial cell interactions while Angiopoietin-2 (Ang-2) is a functional antagonist of Ang-1 and leads to marked vessel regression in tumours in the absence of VEGF-A." (PMID 12942123, 2003). "The review further outlines pharmacodynamic anchors-hyperpolarized 13C-pyruvate MRI (kPL), soluble ANGPT2, and spatial NT5E/ADORA2A modules-to operationalize a bench-to-biomarker-to-bedside loop using organoid-immune co-cultures, humanized/xenograft systems, and ex vivo tumor slices." (PMID 41943838, 2026). "In summary, IFN-γ restrains the expression of Tie2 and ANGPT2 in ECs but not in tumor cells." (PMID 40370455, 2025). "Interestingly, anti-ANGPT2 treatment improved vascular integrity and decreased AM discrepancy, especially VCAM-1 and L-selectin, which released sequestered T cells from the periphery into the central tumor areas and reversed the immune-excluded phenotype." (PMID 39107856, 2024). "Notably, high MYBL1 levels were associated with poor prognosis in HCC patients, and MYBL1 was identified as a promotor of tumor angiogenesis and sorafenib resistance in HCC cells stably expressing MYBL1 (HepG2-MYBL1 cells) by activation of angiopoietin 2 (ANGPT2)." (PMID 38835346, 2024). "Blood LDH and ANGPT-2 indicate that non-responding tumours may have a hypoxic microenvironment resistant to radiotherapy." (PMID 36718357, 2023). "Tumor‐borne Angpt2 promotes angiogenesis in zebrafish embryos in vivo and works in a paracrine manner on ECs; this implies that Angpt2 might play an active role within the TME in the crosstalk between tumor cells and ECs." (PMID 35266635, 2022). "Unlike ANGPT-1, ANGPT-2 plays a crucial role with VEGF-A in tumor lymphangiogenesis." (PMID 33172072, 2020). "In fact, the presence of angiogenic molecules, such as vascular endothelial growth factor (VEGF) and angiopoietin 2 (ANG2), within the TME may better drive immune cells towards the tumor, by altering the expression of adhesion molecules on endothelial cells (ECs) and immune cells." (PMID 32867142, 2020).
tumor (continued). "Therefore, interventions with high doses of folic acid seem to exert tumor progression dependent on upregulation of Angiopoietins and VEGF-C, whereas, low levels of folic acid can induce down-regulation in the VEGF gene and the ratio of ANGPT2/VEGF." (PMID 31619709, 2019). "Indeed, targeting the angiopoietin 2 (ANG2)/Tie2 pathway, with an anti-ANG2 antibody, inhibits tumor growth and metastasis by disabling the pro-angiogenic activity of Tie2-expressing monocytes/macrophages and impeding the emergence of evasive resistance to antiangiogenic therapy." (PMID 28955335, 2017). "The results showed that the expression levels of vascular endothelial growth factor A (VEGFA), angiopoietin-2 (ANGPT2), and tissue plasminogen activator (PLAT) were suppressed in ADAM9-silenced cells, which in turn leads to decreases in angiogenesis, vascular remodeling, and tumor growth in vivo." (PMID 29118335, 2017). "Moreover, rCTHRC1 upregulated angiopoietin-2 (Ang-2), a Tie2 receptor ligand, through ERK-dependent activation of AP-1 in ECs, resulting in recruitment of Tie2-expressing monocytes (TEMs) to CTHRC1-overexpressing tumor tissues." (PMID 27686285, 2016). "Gene expression of ANGPT2 showed no variance in smaller tumours with and without lymphatic spread." (PMID 26044849, 2015). "Furthermore, GLI1 facilitates tumor aggressiveness by orchestrating the tumor microenvironment (TME); it drives angiogenesis through the direct transcriptional upregulation of vascular endothelial growth factor (VEGFA) and Angiopoietin-2 (ANGPT2), essential for the hyper-vascularized nature of GBM." (PMID 41596413, 2026). "Therefore, ANGPT-2 and VEGFR-2 co-targeting could be effective in tumor therapy." (PMID 38213742, 2024). "Angiogenesis-related genes (FLT1, KDR, SPARC, INSR, ANGPT2, and FLT4) and MHC-I molecules (HLA-A, HLA-B, HLA-C, HLA-E, and HLA-F) were highly expressed in cluster 3 ECs, indicating that the cells may function as antigen-presenting cells and promote tumor parenchymal angiogenesis." (PMID 37533434, 2023). "This signature was set up on fresh tumor tissue, which is often not available in retrospective series, but we have previously shown that the neoangiogenic transcriptomic signature is equivalent to the immunohistochemical expression of angiopoietin-2 (ANGPT2) in HCC tissue." (PMID 36158651, 2022). "ANGPT2 was rarely expressed in nontumor brain tissues and peripheral GBM regions but was detected in approximately 25% of tumor vessels in the tumor center." (PMID 36828931, 2023). "The ECs-related genes such as ANGPT2, CD34, LYVE1, VWF and PECAM1 were highly upregulated in the vascularized tumor tissue as compared to non-vascularized tissue due to the presence of BVs." (PMID 34754042, 2021). "Statistical differences among the ANGPT2 mRNA expression and TNM stage, tumor size in SQC were also not observed." (PMID 31892982, 2020). "However, whether ANGPT2 is carried by tumor-derived exosomes has not been reported." (PMID 32183816, 2020). "In moderately differentiated tumours, gene expression of VEGF and ANGPT2 were higher in tumours without lymphatic spread; only EBFNB2 showed here a higher gene expression." (PMID 26044849, 2015). "Interestingly, although not significant, we observed a gradual increase in angiopoietin-2, FAP, and VEGF-A levels, as tumor grade increased." (PMID 39511039, 2024). "In monocytes, VCAN expression was higher in adjacent tissue samples than tumor samples (P value-adj = 9.99E − 84); ANGPT2 was not highly expressed in immune cells of tumor samples or adjacent tissue samples; MS4A4A was highly expressed in monocytes of tumor samples (P value-adj = 1.02E − 14)." (PMID 36569220, 2022). "Particularly, ANGPT2 and CCL2 were specifically released by the sMSCs leading to the much more aggressive tumor growth, although no superior production of other potent angiogenic molecules like VEGFs was seen in the sMSCs compared to other MSCs (unpublished data)." (PMID 25883937, 2015).
tumor (continued). "Tumor expression levels of miR-126 did not significantly differ between LC-COPD and LC patients, whereas in the former patients, an almost significant decrease in EGFL-7 expression was observed (p = 0.073), together with a decrease in TOM-1 and CRK expression and a rise in angiopoietin-2 content." (PMID 29371906, 2018).
cancer (103 papers, 2012 to 2025). A tumor composed of atypical neoplastic, often pleomorphic cells that invade other tissues. "For example, scRNA-seq has uncovered TEC populations with high expression of angiopoietin-2 (Ang-2), a marker associated with poor prognosis in cancer patients." (PMID 40121354, 2025). "Serum ANGPT-2 is elevated in multiple cancers and diseases associated with microvasculature dysfunction." (PMID 38182581, 2024). "Previous studies found that ANGPT2 was related to cancer-associated microenvironment organization along with metastatic formation." (PMID 36569220, 2022). "As the level of ANGPT2 is up-regulated in plasma in cancer patients and associated with poor prognosis, ANGPT2 can be used as a biomarker for cancer treatment." (PMID 32874130, 2020). "Angiopoietin 2 (Ang2), being the antagonist of Ang1 that stabilizes nascent vessels by recruiting mural cells, is implicated in the formation of unstable and leakier vessels and it is upregulated in many cancers." (PMID 36672695, 2023). "Conversely, loss of ARID1A may increase the risk of steatohepatitis and cancer progression by altering immunity in vivo or tumorigenesis via activation of angiopoietin-2 (ANGPT2) transcription in vitro and angiogenesis in vivo." (PMID 36844227, 2023). "A member of the Ang family called angiopoietin-2 (Ang2), involved in developmental angiogenesis and in the growth of human cancers, may have mortality associations." (PMID 36830687, 2023). "Residual tumor cells release hypoxia-inducible factor (HIF), leading to increased vascular endothelial growth factor (VEGF), fibroblast growth factor (FGF) and angiopoietin-2 (Ang-2), promotes tumor angiogenesis and progression, increasing the risk of cancer recurrence and metastasis." (PMID 36591442, 2022). "ANGPT2 encodes for the angiopoietin-2 protein, which competitively inhibits angiopoietin-1 by specifically binding to the angiopoietin receptor, and thereby modulates the growth and progression of several cancers." (PMID 32644941, 2020). "In addition, genes associated with cancer progression (e.g., Vegfr2, Angpt2, and Kdr) were suppressed at 9 and 13 weeks post instillation." (PMID 30984195, 2019). "Conversely, ARID1A loss may increase the risk for steatohepatitis and cancer progression by altering immunity in vivo or tumorigenesis by activating angiopoietin-2 (ANGPT2) transcription in vitro and causing angiogenesis in vivo." (PMID 31238554, 2019). "In addition, some studies have shown ANGPT2 is prognostic biomarker in cancers, and whether ANGPT2 is associated with the outcome or can be used to risk stratification in patients with AAD is also needed to be confirmed." (PMID 35004874, 2021). "Additionally, the combination of TGF-β1 and angiopoietin-2 could strongly predict the relative risk of poor prognosis in severe cancer stages in our study." (PMID 33806004, 2021). "However, a high level of angiopoietin-2 could be associated with the trend for shorter survival time and predict the severe cancer stages with an adjusted OR equivalent to 23.22." (PMID 33806004, 2021). "However, there are few reports regarding Angpt2 polymorphisms in various types of cancers." (PMID 31929743, 2020). "Among 33 different types of cancer, we found that high ANGPT2 and mesenchymal marker expressions all had poor prognostic impacts on three cancer types including GC." (PMID 39309430, 2024). "Several crucial transcription factors, including STAT3, HOXD9, and HOXB5, are known to bind to ANGPT2 promoter regions, thereby activating ANGPT2 expression and promoting malignant phenotypes in cancer cells 58-60." (PMID 39309430, 2024). "While Angpt1 counteracts hyperpermeability, Angiopoietin 2 (Angpt2) is upregulated in human cancer and its activation weakens the vascular barrier." (PMID 38426110, 2024). "Patients with advanced disease had significantly higher expression of the HGF and ANGPT2 genes compared to patients with early-stage carcinoma." (PMID 39302921, 2024).
cancer (continued). "Well established examples are vascular endothelial growth factor (VEGF) and angiopoietin-2 (Ang-2), both of which are key regulators of angiogenesis and, hence, important cancer therapeutic targets." (PMID 36672343, 2023). "ROC curves further demonstrated that the expression level of ANGPT2 can effectively distinguish between carcinoma and paracancerous tissues." (PMID 37616050, 2023). "These exosomes are introduced into HUVECs by endocytosis, and increased expression of ANGPT2 induces angiogenesis that promotes cancer progression." (PMID 35765040, 2022). "ANGPT2 is expressed by endothelial cells, cancer cells, and some immune cells depending on the hypoxia context or upon stimulation by different cytokines or growth factors such as TNF-α, TGF-β, and VEGF." (PMID 35935946, 2022). "To further verify ANGPT2 expression in GC specimens, we found that ANGPT2 was highly expressed in cancer tissues from patients with GC than in para-cancerous tissues." (PMID 36172371, 2022). "In this study, we predicted HIF-1α and ANGPT2 as regulators of HCC by the OncoMir cancer database and showed a strong positive correlation with HIF-1α and ANGPT2 gene expression in HCC patients." (PMID 35163556, 2022). "In pathological conditions, such as cancer, AKT inactivation, caused by weak ANGPT1-TIE2 signaling, results in the activation of Foxo1 and the expression of ANGPT2." (PMID 35203640, 2022). "Suppression of the ANGPT2/Tie2 axis is a promising target because studies have shown the role of this factor in angiogenesis of cancer angiogenesis and in inflammation." (PMID 35765040, 2022). "Both VEGFA and ANGPT2 have been used as biomarkers for measuring the efficacy of various drugs used in cancer treatment." (PMID 35052372, 2021). "Angiopoietin-2 (Ang2) is a secreted ligand whose expression is increased markedly in several pathologies, including sepsis, age-related macular degeneration, and cancer, where it contributes to disease progression." (PMID 34153320, 2021). "In conclusion, our study verifies that miR-145-5p affects the proliferation, migration and invasion of cancer cells via the ANGPT2/NOD_LIKE_RECEPTOR axis, which helps the mechanism research underlying GC cancer progression." (PMID 32874130, 2020). "ANGPT-2 is a secreted glycoprotein and plays a key role in angiogenesis in cancer neovascularization." (PMID 32409702, 2020). "More evidence has revealed that Angiopoietin-2 (ANGPT2, Ang2) can function on angiogenesis and directly stimulate the proliferation of cancer cells." (PMID 32874130, 2020). "This assumes significance in view of the fact that angiopoietin-2 has been shown to play a key role in angiogenesis in the process of cancer progression and metastasis in patients with breast cancer." (PMID 33082849, 2020). "AMG-386 is a small peptibody against the TIE2 ligands ANGPT1 and ANGPT2, and its efficacy is currently tested against different types of cancer, including BCa, in phase 1 and 2, clinical trials (NCT00511459, NCT00807859, and NCT01042379)." (PMID 32260072, 2020). "As with vascular endothelial growth factor (VEGF), the role of Angpt2 has been characterized as being pro-angiogenic or pro-inflammatory in cancer progression 21-24." (PMID 31929743, 2020). "Investigation of the expression pattern of cancer‐related genes in 4C11− and 4C11+ cells revealed that Vegfc and Angpt2 were among the top 10 upregulated genes." (PMID 31069961, 2019). "Lung cancer is the most common malignant tumor with increasing angiopoietin-2 (Ang-2) and a high rate of metastasis." (PMID 29560103, 2018). "In addition, blocking ANGPT2 can effectively improve cancer immunotherapy via downregulation of Programmed death ligand-1 (PD-L1)." (PMID 36907878, 2023). "Conversely, ANGPT2 has also been shown to promote angiogenesis in cancers." (PMID 37616050, 2023).
cancer (continued). "In addition, monoclonal antibodies directly targeting VEGF, PDGF, angiopoietin-2 (Ang-2), and their receptors are also used in the clinical or pre-clinical cancer treatment." (PMID 36793021, 2023). "More importantly, blocking ANGPT2 can effectively improve cancer immunotherapy." (PMID 36907878, 2023). "Several ANGPT2-specific antibodies have been developed and are currently being tested in combination with other targeted therapies in clinical trials for patients with cancer." (PMID 37843277, 2023). "In fact, many target genes of YAP have been proved to participate in cancer-associated angiogenesis through activation of ECs, especially the cytokines such as CTGF, cyr61, MFAP5, and angiopoietin-2, which could secreted by cancer cells." (PMID 36226237, 2022). "However, in endothelial cells a pro-angiogenic role of ANGPT2 through an integrin axis and a Tie-2-independent mechanism was described as promoting cancer invasiveness, therefore, being considered as an important therapeutic target." (PMID 35513564, 2022). "Therefore, our results uncover a novel mechanism for upregulation of ANGPT2 in cancer and indicate an oncogenic role for MYBL1 in HCC angiogenesis and sorafenib resistance." (PMID 35987690, 2022). "ANGPT2 is a vascular growth factor involved in angiogenesis, one of the main hallmarks of cancer." (PMID 35064782, 2022). "In many other cancer types, ANGPT2 has been suggested as a pro-cancerous factor." (PMID 35513564, 2022). "This highlights the potential efficiency of Angpt2 inhibitory strategies for cancer therapy." (PMID 35884919, 2022). "Angiopoietin-2 (Ang-2) is a growth factor belonging to one of the main pathways of angiogenesis; it is upregulated upon inflammatory stimuli and conditions such as hypoxia and cancer." (PMID 35740350, 2022). "On the other hand, Angiopoietin-2 acts as an inhibitor of the Angiopoietin-1/Tie2 signaling pathways, thus facilitating the destabilization of quiescent endothelium in cases of inflammation and cancer." (PMID 34833409, 2021). "This study reports on the association between 5 SNPs of the Angpt2 gene (rs2442598, rs734701, rs1823375, 11137037, and rs12674822) and CRC susceptibility as well as clinical outcomes in 379 patients with CRC and in 1,043 cancer-free healthy controls." (PMID 31929743, 2020). "In addition, MTT and Transwell assays were performed to verify the effect of ANGPT2 on cancer cell proliferation, migration and invasion." (PMID 32874130, 2020). "Cancer cell proliferation was significantly inhibited in the si-ANGPT2 group." (PMID 32874130, 2020). "The plasma level of angiopoietin-2 was lower in cancer patients compared to controls, median 1362.9 pg/mL (IQR 1223.1–1707.7, range 750.4–2054.2) vs. 1868.5 (IQR 1531.0–2338.4, range 1248.7–5489.9) (Mann-Whitney U test, p = 0.0257; Shapiro-Wilk test, p < 0.0001; Kolmogorov-Smirnov test, p < 0.0100)." (PMID 32799882, 2020). "It is reported that ANGPT2 is an important molecular determinant of cancer cell metastasis." (PMID 28977900, 2017). "Several evidences support the direct role of angiopoietin-2 in cancer prognosis." (PMID 24373251, 2013). "Therefore, illumination the molecular mechanisms of deregulation of ANGPT2 may provide new approaches for the development of targeted cancer therapies." (PMID 35987690, 2022). "ANGPT2 blockade could provide therapeutic benefits of cancer." (PMID 36569220, 2022). "Other signature genes, including ITGA5, ANGPT2, and CD44, have recognized roles in cancer progression and are already under investigation as therapeutic targets." (PMID 41374933, 2025). "USP5 stabilized STAT3 via its deubiquitination function, thereby enhancing the production of pro-angiogenic factors by cancer cells, including VEGF, ANGPT2, and CXCL1." (PMID 40691441, 2025).